RAD51 (RAD51 recombinase)
Diseases named in the same sentence as RAD51 in open-access papers (continued):
Sharing a sentence is not in itself a finding about the gene and the disease.
cancer (continued). "Li-Qing Du and colleague noticed that this drug inhibit the expression of RAD51 in cancer cells." (PMID 35676421, 2022). "Additionally, polymorphisms in predicted miRNA target sites of MRE11, NBS1, RAD51 and RAD52 have been associated with different cancer risks, susceptibility, and survival." (PMID 35328651, 2022). "Results showed that RAD51 was significantly overexpressed in 28 types of cancer." (PMID 35359409, 2022). "In addition, it facilitates the hiring of HR-related key proteins RAD51 and BRCA1 to DNA damage sites for repair, therefore it also prevents cancer cells from proliferating and causing cell cycle arrest, which helps them escape the threat and thus survive." (PMID 36575478, 2022). "Thus, elevated RAD51 expression can help cancer cell survival and evolution by acting at multiple levels." (PMID 36428789, 2022). "Results showed that RAD51 was positively correlated with the stemness of 27 types of cancer." (PMID 35359409, 2022). "Rad51 is also engaged in the tumor initiation and development in multiple cancer types." (PMID 35875146, 2022). "Our findings substantially agree with the idea that Wee1 is rapidly recruited at DSBs in response to DNA damage via ATM-γH2AX-MDC1, driving Wee1 to recruit downstream HR repair proteins BRCA1 and RAD51 to DNA damage sites, as well as allowing cancer cells to escape damage and survive." (PMID 36575478, 2022). "RAD51, a critical protein for DNA repairment, has been found to associate with multiple cancer types, but, so far, a systematic pan-cancer analysis of RAD51 has not been done yet." (PMID 35359409, 2022). "Therefore, this study proposed that RAD51 can be a predictive factor for ICB therapy in these cancer types." (PMID 35359409, 2022). "Consistent with that, we show that CB inhibits the expression of several genes associated with DNA repair pathways—including RAD51 and DNA ligase I (LIG1) and consequently inhibits the heightened DNA repair activity that cancer cells employ to survive and proliferate." (PMID 35610507, 2022). "However, RAD51 involvement in cell survival in genotoxic conditions and its different abilities for AS in cancer and normal cells makes it a promising target for anticancer applications." (PMID 35163785, 2022). "Consistent with this hypothesis, we demonstrate that RAD51 inhibitors combined with olaparib increased accumulation of DNA damage, producing a synergistic effect on cancer cell growth inhibition." (PMID 35646698, 2022). "Collectively, these findings show that RAD51 inhibition-mediated IRF1 upregulation, a downstream component of ATR/Chk1 signaling, is a critical mechanism underlying PD-L1 expression regulation in cancer cells." (PMID 35646698, 2022). "Results showed that 15 cancer types were found to significantly overexpress RAD51." (PMID 35359409, 2022). "Therefore, direct targeting of RAD51 to reduce its activity and expression is one strategy to sensitize and overcome cancer cells resistant to conventional DNA damage therapy." (PMID 36361910, 2022). "Interestingly, results revealed that proliferating T cells was the cell type that expressed the highest RAD51 across most of the cancer samples analyzed." (PMID 35359409, 2022). "Treatment of cancer cells with a DNA breaking agent led to upregulation of immune-related pathways such as PD-1 and Interferon Signaling whereas this upregulation was either prevented or reversed by RAD51 inhibitor." (PMID 36428789, 2022). "Given the crucial role for RAD51 in repairing DSBs induced by chemotherapy, we explored whether RAD51 inhibition could sensitize cancer cells to chemotherapeutic drugs." (PMID 35646698, 2022). "It was previously reported that Rad51 protein is overexpressed in cancer cells." (PMID 36015440, 2022). "Pan-cancer analyses aimed at depicting the immunological role of RAD51 are critical in determining the types of cancers that may benefit from anti-RAD51 immunotherapy or immunotherapy prediction by RAD51." (PMID 35359409, 2022).
cancer (continued). "Cancer cells adapt cellular metabolism to cope with their high proliferation rate, hence, it is reasonable that cancer cells have a higher expression of RAD51 than normal cells." (PMID 35359409, 2022). "RAD51 has been explored as a pharmacological target in two different ways, first, in cancers known to overexpress RAD51, compounds with single-agent activity have been described that exploit overexpression by inducing formation of toxic RAD51 complexes on undamaged DNA." (PMID 35463312, 2022). "Some Rad51 inhibitors have shown application potentials in cancer therapy." (PMID 35220392, 2022). "In the present study, we demonstrated that PAs have cytoprotective effects on normal human CD4+ T lymphocytes but not on Jurkat or K562 cancer cells, and such protection is associated with the induction of the alternative splicing of RAD51 pre-mRNA." (PMID 35163785, 2022). "Overall, our findings establish that RAD51 inhibition could be used as a new prospect for cancer treatment with the potential to enhance the therapeutic window of many established therapeutic strategies across multiple cancer indications." (PMID 35646698, 2022). "A subsequent study used publicly available transcriptional profiling data to demonstrate that BRD4 inhibition modulates a previously validated HR defect gene signature, though finding minimal impact on BRCA1 or RAD51 expression in cell lines of multiple cancer types." (PMID 35681619, 2022). "Although the function of RAD51 in cell growth has been well defined, the association of RAD51 and human diseases has not been studied wildly and the clinical use of RAD51 as a biomarker for cancer has not been developed." (PMID 35359409, 2022). "RAD51 was inhibited in cancer cell lines using shRNAs and a small molecule inhibitor." (PMID 36428789, 2022). "Moreover, Rad51 inhibition can be achieved by nanoscale material- or cell-penetrating peptide (CPP)-mediated direct delivery of Nanog-C/CD2 peptides into somatic cancer cells." (PMID 35220392, 2022). "Post-translational regulation of Rad51 participates in the activation or stabilization of Rad51 protein, which may provide novel anti-tumor targets for cancer management." (PMID 35875146, 2022). "RAD51 expression was different across immune subtypes in 11 cancer types." (PMID 35359409, 2022). "This study was also interested in the prognostic value of RAD51 in cancers." (PMID 35359409, 2022). "In this scenario, we investigated whether the Nanog fragment derived from mouse ES cells could serve as an exogenous peptide inhibitor to interrupt endogenous Rad51 of human cancer cells." (PMID 35220392, 2022). "RAD51 was also proposed as a potential therapeutic target in cancer." (PMID 36139526, 2022). "LGG was the only cancer type whose stroma score was weakly and positively correlated to RAD51." (PMID 35359409, 2022). "RAD51 is an ATP-dependent recombinase, recruited by BRCA2to mediateDNA double-strand breaks repair through homologous recombination andrepresents an attractive cancer drug target." (PMID 35978685, 2022). "Data suggested that the overexpression of RAD51 might promote cancer resistance to chemotherapy and radiotherapy." (PMID 35359409, 2022). "Moreover, the knockdown of RAD51 increased the anti-cancer activity of alpinumisoflavone in preclinical CRC models, while the alpinumisoflavone effect was abolished by the up-regulation of RAD51." (PMID 35330396, 2022). "Therefore, this study proposed that the levels of RAD51 in these cancer types depended on proliferating T cells if there is a large proportion of this type of T cells." (PMID 35359409, 2022). "Thus, univariate overall survival Cox regression analysis of RAD51 was conducted across 33 cancer types." (PMID 35359409, 2022). "Rad51 is an oncogene that has been involved in a variety of cancers." (PMID 34115569, 2021).
cancer (continued). "Therefore, cancers with loss‐of function mutations in HR pathway components such as BRCA1, ATM, ATR, RAD51, and FANC genes are susceptible to treatment with PARP inhibitors." (PMID 33660437, 2021). "This means that there may be a conserved gene regulatory circuit in which RAD51 and E-box binding proteins are involved, and that activating this regulatory circuit is beneficial to cancer cells." (PMID 34067336, 2021). "The significantly down-regulated expression of RAD51 by OXY may be the key mechanism by which OXY mediates its anticancer effect in consideration of RAD51 being overexpressed in a variety of cancer cells." (PMID 34305605, 2021). "How could the many RAD51-overproducing cancers proliferate and replicate their DNA with stalled reversed forks?" (PMID 34571923, 2021). "Intriguingly, this role of RAD51 is also related to the function of autophagy in cancers." (PMID 34067336, 2021). "Rad51, a DNA-repair-related gene, has been reported to be involved in multiple cancers." (PMID 34115569, 2021). "BRCAness allows for the expansion of the somatic lethality approach to tumors carrying deficiencies in tumor suppressor genes involved in homologous recombination (HR) defective cancers, possessing BRCA1, BRCA2, ATM, ATR, FANC, RAD51, BRIP1, or PALB2 mutations." (PMID 34639169, 2021). "Owing to its multifaceted roles in various cancers, RAD51 might have universal predictive value and warrants further investigation." (PMID 33952262, 2021). "RAD51 overexpression of is generally due to overactivation of the promoter in cancer cells." (PMID 34316706, 2021). "Human RAD51 is a RecA ortholog and is upregulated in many diverse cancers." (PMID 34571923, 2021). "Thus, miR-506-3p can enhance the efficacy of anti-cancer drugs and can sensitize cancer cells to DNA damage by targeting RAD51, GLI3, and SPHK1." (PMID 33766100, 2021). "The association of RAD51 with relapse/survival was validated in a carboplatin monotherapy SCOTROC4 clinical trial cohort (n = 264) and was predominantly noted in HR‐proficient cancers (Myriad HRDscore < 42)." (PMID 33709473, 2021). "As expected, the RAD51 gene is highly expressed in most cancer cell lines." (PMID 34067336, 2021). "Moreover, in addition to RAGE, other repair factors such as BRCA1, RAD51 and Mdm2 are known to express their multiple splice variants in SCLC and other cancers." (PMID 34200336, 2021). "Therefore, to test the effect of CAM833 on RAD51 clustering, we used SMLM on patient-derived EUFA423 cells bearing compound heterozygosity for the cancer-associated BRCA2 truncating alleles 7691insAT and 9000insA." (PMID 33662256, 2021). "We found that HGK could improve the sensitivity of cancer cells to doxorubicin by inhibiting the expression of RAD51." (PMID 34575923, 2021). "Finally, we looked into the relationship between Cancer-associated fibroblast (CAF) and Rad51 expression." (PMID 34115569, 2021). "We looked for suggestions in human cancer transcriptomes of mRNAs of human proteins that might remove or prevent reversed forks, and thus allow RAD51-overexpressing cancers to replicate." (PMID 34571923, 2021). "In addition to inhibiting calmodulin and downregulating AKT activity, TFP was reported to inhibit DNA repair efficiency in cancer cells by decreasing expression of several DNA repair proteins including RAD51, found to be upregulated in PAH cells." (PMID 33805714, 2021). "Furthermore, RAD51 appears as a valuable therapeutic target, especially in tumors prone to accumulate DNA breaks, such as cancers showing strongly rearranged genomes." (PMID 34208195, 2021). "Several studies have shown that combinations of RAD51 and ATM variants may increase the risk for cancer development." (PMID 33778923, 2021).
cancer (continued). "As genomic instability is almost inherent in cancer cells, it is tempting to speculate that over-activation of RAD51 could be part of a compensation mechanism to protect cells from excessive genetic instability." (PMID 34208195, 2021). "Overexpression of Rad51, an essential protein involved in DNA DSB repair by HR pathway, is associated with a more aggressive cancer phenotype and treatment resistance in various tumors, including ovarian, cervical, prostate, pancreatic, colorectal, and malignant gliomas." (PMID 33673439, 2021). "For example, among 31 types of cancer, RAD51 was significantly overexpressed in 21 cancers." (PMID 34067336, 2021). "Remarkably, FA patients with RAD51 mutation (FA-R) do not develop cancers, although they present other developmental anomalies related to FA." (PMID 34316706, 2021). "Therefore, VPA probably directly upregulates RFWD3 and then initiates Rad51 ubiquitination to disrupt the HR function so as to enhance IR effect for killing cancer cells." (PMID 33842359, 2021). "The important role of RAD51 in DNA repair made it an attractive pharmacological target in cancer treatment and has motivated investigators to search for small molecule inhibitors that could disrupt its functions." (PMID 34208195, 2021). "We highlight that the central HR factor, RAD51, has yet to be well characterized in vivo and, unlike most HR factors, its inactivation has not been associated with cancer predisposition, revealing what we call the “RAD51 paradox”." (PMID 33923105, 2021). "Here, we found pronounced RAD51 expression in 19 kinds of cancers, implying that RAD51 might mainly function as an oncogene." (PMID 33952262, 2021). "Taken together, we suggest that the treatment of cancer cells with CHK1 inhibitor could not only affect the replication checkpoint, but could also interfere with RAD51 foci formation and, thus, induce HR deficiency." (PMID 34208195, 2021). "Taken together with the case studies above, the RAD51–autophagy interaction seems to have the nature of a two-faced role of autophagy in relation to cancers, where a different point of view may be required to understand the RAD51–autophage axis." (PMID 34067336, 2021). "Amongst these, ‘breast cancer 1, early onset (BRCA1)’; ‘BRCA1 associated RING domain 1 (BARD1)’; ‘BRCA1 interacting protein C-terminal helicase 1 (BRIP1)’; ‘H2A histone family, member X (H2AFX)’ and RAD51." (PMID 33491125, 2021). "RAD51 is an important target for the development of novel anti-cancer therapies." (PMID 34208492, 2021). "According to this hypothesis, only mutations that suppress RAD51 expression or its loading and/or stabilization on damaged DNA (such as mutations in BRCA1, BRCA2 or PALB2 or other HR factors) should confer cancer predisposition." (PMID 34316706, 2021). "Transcription factors that regulate RAD51 transcription could, thus, be key in the response of cancer cells to DNA-damaging treatments." (PMID 34208195, 2021). "As such, understanding the function and regulation of RAD51 is essential for cancer biology." (PMID 33015624, 2020). "IBR120 is an inhibitor that disrupts RAD51 interaction with BRCA2 sensitizing cancer cells to IR." (PMID 32932697, 2020). "Rad51, a critical protein involved in oocyte resilience to apoptosis, is a feasible candidate to promote DNA repair capacity in oocytes and ultimately conserve fertility in women undergoing cancer treatment." (PMID 31947601, 2020). "Understanding mechanistic details of Rad51 in homologous recombination (HR) and repair could facilitate design of novel methods, including CRISPR, for Rad51-targeted cancer treatment." (PMID 37528958, 2020). "Of note, CYT-0851 is another RAD51 inhibitor that was recently approved for a phase 1/2 clinical study in various cancers (NCT03997968) after showing promise in preclinical models, thus may be a potential valuable alternative." (PMID 32572160, 2020).
cancer (continued). "In high PPS20 group, we found increased protein level expression of Cyclin B1, which is a marker of cell proliferation and as well as DNA repair which is consistent with increased RAD51 which is involved in double stranded break repair, tumor progression and resistance to anti-cancer treatments." (PMID 32310997, 2020). "Furthermore, cancer stem cells are resistant to PARPi and exhibit increased RAD51 foci formation after DNA damage." (PMID 33015624, 2020). "Interestingly, inhibition of RAD51 increased the sensitivity of the cancer cells to radiotherapy, which is a potential therapeutic strategy that requires further exploration." (PMID 32190537, 2020). "Given that attenuation of DNA damage repair in AKT-inhibited cancer cells might be due to the decreased efficacy of homology-mediated repair of DNA DSBs, we analyzed the expression of Rad51 recombinase, known as a key protein involved in DSB repair." (PMID 33266502, 2020). "Inactivating RAD51 can have profound effects on genome stability leading to cancer as well as an FA-like syndrome, a rare genetic disorder characterized by bone marrow failure and cancer." (PMID 33015624, 2020). "It is evident from innumerable studies that RAD51 is up regulated in different cancers." (PMID 32458654, 2020). "As it was thought that the T stage was indicative of cancer prognosis, RAD51 mRNA may be regarded as a marker of prognostic value." (PMID 31973027, 2020). "In addition to inactivating pathogenic mutations in RAD51, disruption of the RAD51 regulators, including the RAD51 paralogs, is also correlated with cancer." (PMID 33015624, 2020). "Our data provided supports for additional studies toward the development of enhanced approaches for cancer treatment based on aberrant regulation of RAD51, which may become a potential predicative marker and therapeutic target in neoadjuvant endocrine therapy." (PMID 31506496, 2019). "Not surprisingly, germline and somatic mutations in RAD51 and its mediators have been extensively linked to genetic instability, cancer predisposition and hereditary diseases such as Fanconi anemia." (PMID 31665741, 2019). "Several early studies showed success in inhibiting RAD51 for cancer treatments." (PMID 31375703, 2019). "The clinical and biological functions of RAD51 expression in cancer are still under investigation." (PMID 31889908, 2019). "Our studies support the hypothesis that through the DNA damage and repair machinery RAD51 might contribute to cancer cell glycolysis by regulating the HIF1α transcriptional process." (PMID 31889908, 2019). "Moreover, we investigated the level of RAD51 mRNA in both cancer cell lines after treatment with IPA and in combination with IR." (PMID 31993371, 2019). "Further, it sensitized cancer cells to chemotherapy by directly targeting RAD51 and thus could be of therapeutic importance." (PMID 31608277, 2019). "However, the observed correlations of these papers between two cancers and RAD51 SNPs were inconclusive." (PMID 31886162, 2019). "To further explore whether MUS-KD cells harbored HR defects, we detected RAD51 foci in the presence of UV-induced DNA DSBs, as it has been reported that the inability of cancer cells to form RAD51 foci could be a surrogate for dysfunctional HR." (PMID 31803609, 2019). "However, the size of RAD51 promoter is ~6.5 kb which limits its potential clinical applications, so expanding the list of cancer-specific promoters would be critical." (PMID 29549248, 2018). "RAD51 overexpression may lead to improper hyperrecombination, which might drive regular cells toward neoplastic transformation or further contribute to cancer progression and metastasis." (PMID 30319685, 2018).